LAG3 (lymphocyte activating 3)
Diseases named in the same sentence as LAG3 in open-access papers (continued):
Sharing a sentence is not in itself a finding about the gene and the disease.
ovarian carcinoma (continued). "Currently, only a few early-phase clinical studies (phases 1 and 2) have investigated anti-LAG-3 monoclonal antibodies (mAbs) as monotherapy or in combination with other ICIs such as anti-PD-1 and anti-CTLA-4 in advanced solid tumors, including ovarian cancer." (PMID 41383608, 2025). "Compared to PD-L1, IDO, and LAG-3, TIM-3 showed markedly higher expression levels in ovarian cancer tumors." (PMID 40649775, 2025). "Our findings indicated that LAG3 shows a protective role in acute myeloid leukemia (AML), ovarian cancer, and BRCA." (PMID 39064019, 2024). "In epithelial ovarian cancer (EOC), expression level of LAG-3 in TILs is negatively correlated with patient prognosis." (PMID 39660130, 2024). "Therefore, ICIs via LAG-3 may spread to platinum-resistant ovarian cancer." (PMID 37179337, 2023). "The aim of the review was to analyze studies considering the expression of TIM-3 and LAG-3 in the ovarian cancer microenvironment and considering immunotherapy for ovarian cancer that includes antibodies directed against TIM-3 and LAG-3." (PMID 36359346, 2022). "Meanwhile, these cells also positively expressed T cell exhaustion markers, including LAG3 and PDCD1, indicating that the CD8+ T cells are exhausted after initial activation in ovarian cancer." (PMID 35935940, 2022). "Only PD-1 is expressed at high levels in CD103+ CD8+ TRM cells in ovarian cancer, and the expressions of CTLA-4, Tim-3 and LAG-3 are negligible." (PMID 36077846, 2022). "We then evaluated correlation of T cell exhaustion biomarkers PD1 (PDCD1), CTLA4, LAG3 and HAVCR2 with the expression of CD47 in ovarian cancer." (PMID 34966389, 2021). "ICOS appears to be a particularly relevant immune gene in ovarian cancer, as ICOS and LAG-3 were the only genes determined from our multidimensional analysis that were validated independently in TCGA cohort." (PMID 33747935, 2021). "LAG-3 works primarily through binding of its ligand MHC class II and is, together with PD-1, an important regulator of TILs in ovarian cancer." (PMID 32547707, 2020). "Promising results were observed when treating the mice with antibodies targeting either LAG3 or TIM3 in combination with other immunotherapy treatments, encouraging further investigation in patients with ovarian cancer." (PMID 33352957, 2020). "A mouse model of ovarian cancer has shown that in vivo treatment with single agent antibodies against PD-1, CTLA-4, or LAG-3 leads to compensatory upregulation of other checkpoint inhibitor pathways in tumour-associated lymphocytes." (PMID 32937961, 2020). "Both LAG3 and TIM3 have been investigated as targets for inhibitory monoclonal antibodies in ovarian mice bearing ovarian cancer models and showed promising results when used in combination with other immunotherapies." (PMID 33352957, 2020). "We analyzed the expression levels of the checkpoint receptors in the three ovarian cancer subtypes responsible for decreasing T cell bioactivity, including PDCD1 (PD1), CTLA4, LAG-3, and TIM-3." (PMID 33282564, 2020). "At first, we constructed a Her2-specific CAR in lentiviral vector with specific cytotoxicity to Her2+ human ovarian cancer SKOV3 cells, and its combination with one of sh-PD-1, sh-Tim-3, sh-Lag-3, or scramble shRNA." (PMID 31511513, 2019). "Accumulating evidence has delineated that LAG-3 is over-expressed on tumor-infiltrating CD8+ T cells in various tumor types, such as ovarian cancer, hepatocellular carcinoma, renal cell carcinomas and other solid tumors." (PMID 30603054, 2018). "Co-upregulation of PD-1 and LAG-3 was observed in CD8+ T cells specific for viral or tumor antigens during chronic infection with lymphocytic choriomeningitis virus and human ovarian cancer." (PMID 29914540, 2018). "In comparison, targeting PD-1/PD-L1 pathway and LAG-3 has been shown to synergistically increase the frequency and restore effector functions of tumour-specific CD8+ T cells in human ovarian cancer." (PMID 28537896, 2017).
ovarian carcinoma (continued). "The results indicate that EMT in ovarian cancer cells promotes interactions between cancer cells and T cells through the LGALS3 - LAG3 axis, which could increase T cell exhaustion in infiltrated tumors, dampening antitumor immunity." (PMID 38086828, 2023). "A further implication from our study points to LAG-3 and KLRG1 checkpoint receptors that may contribute to the immunotherapy resistance in patients with ovarian cancer." (PMID 38032111, 2023). "We next observed that SPP1 expression was positively related with immune-checkpoint, such as CD274, CTLA-4, LAG3 and TIGIT, suggesting that SPP1 may play an important role in immune tolerance of ovarian cancer." (PMID 36585688, 2022). "Immune‐checkpoint molecules PD‐1, LAG3, CTLA4, TIGIT, and HAVCR2 (TIM‐3) have been identified and studied in various cancers including liver hepatocellular carcinoma, lung adenocarcinoma, stomach adenocarcinoma, ovarian cancer, and peritoneal carcinoma." (PMID 35184420, 2022). "In addition to the well-studied PD-1, PD-L1 and CTLA-4 in ovarian cancer, the role of TIM-3 and LAG-3 expression seems promising." (PMID 36359346, 2022). "Two independent studies have reported the compensatory upregulation of ICs, including lymphocyte activation gene-3 (LAG-3), T-cell immunoglobulin and mucin domain-3 (TIM-3) and CTLA-4, on CD8+ T cells after PD-1 blockade in immunocompetent murine models of ovarian cancer and lung adenocarcinoma." (PMID 33467713, 2021). "Relatlimab, an anti-LAG-3 mAb, is being trialled with and without nivolumab for various solid cancers including ovarian cancer (NCT01968109)." (PMID 32937961, 2020). "A recent retrospective analysis of epithelial ovarian cancer patients receiving ICB immunotherapy of targets including PD-1, PD-L1, CTLA-4, and LAG-3 alone or in combination, found that over 50% of patients suffer disease progression requiring early discontinuation of therapy." (PMID 32937961, 2020). "Thus, we have initiated the first clinical study treating patients with ovarian cancer with combinational therapy consisting of ACT, anti-PD1, anti-CTLA4, and anti-LAG3 (ClinicalTrials.gov identifier: NTC04611126)." (PMID 33352957, 2020). "Different immune checkpoints seem to be of importance in priming and effector phase, as directly shown for the epithelial ovarian cancer model, where LAG-3 blockade did not influence the effector function of already primed tumor-infiltrating T cells." (PMID 29535740, 2018). "The synergistic effect of PD-1 and LAG-3 in promoting tumor immune escape is suggested by studies on CD8+ T cells specific for NY-ESO-1 present in peripheral blood and tumor site of patients with ovarian cancer." (PMID 26700461, 2016). "We could speculate that the low activity of T cells in immunologically non-responding patients with ovarian cancer may be more affected by their potentially upregulated LAG-3 and KLRG1 coinhibitory/checkpoint receptors than PD-1 receptors." (PMID 38032111, 2023). "Notably, our study found that crucial immune repressive receptors—which have gained significant attention in ovarian cancer research, such as TIM3, CSF1R, CTLA4, PD1, and LAG3 as well as inhibitory enzymes such as IDO1—were closely related to ALOX5AP expression." (PMID 34094977, 2021). "However, since ovarian cancer has not shown encouraging responses to immunotherapy yet, we propose new targets such as the immune checkpoints LAG3 and TIM3 based on our gene expression analyses." (PMID 33352957, 2020). "It is tempting to speculate that expression profiling of LAG-3, together with PD-1, may be a simple way to enrich for tumor-infiltrating T cells that highly co-express multiple checkpoints and co-stimulators, as has been reported for PD-1high CD8 T cells from NSCLC and ovarian cancer." (PMID 37795090, 2023).
ovarian carcinoma (continued). "To further demonstrate the potential collaboration between LAG3 and PD1 in promoting T cell tolerance in the tumor microenvironment, we asked whether PD1 and LAG3 are co-expressed on tumor infiltrating T lymphocytes (TILs) of murine ovarian cancer in C57BL/6 mice." (PMID 26318293, 2015). "In the total ovarian cancer cohort (HGSOC and non-HGSOC), there was a weak negative significant correlation between TIM-3 and age (r = −0.291) and a moderately positive significant correlation between TIM-3 and LAG-3 (r = 0.609)." (PMID 40649775, 2025).
Autoimmunity (74 papers, 2014 to 2025). The occurrence of an immune reaction against the organism's own cells or tissues. "The presence of deficiencies in LAG-3 has been observed to be linked with autoimmune disorders, whereas the excessive expression of LAG-3 within the tumor microenvironment hinders immune responses, particularly those mediated by lymphocytes, thereby facilitating immune evasion." (PMID 39331884, 2024). "In the B6.SJL mice model, LAG-3 blockade or deficiency may cause elevated susceptibility to Hg-induced autoimmunity, as well as unresponsiveness to tolerance induction." (PMID 30603054, 2018). "PD-1, Tim-3 and LAG-3 are co-inhibitory receptors that are critical for controlling autoimmunity: studies with blocking antibodies as well as gene-deficient mice demonstrated that these pathways, individually or synergistically, play important roles in type 1 diabetes and other autoimmune diseases." (PMID 28356069, 2017). "We thus evaluated mercury-induced autoimmunity in LAG-3-deficient B6.SJL mice." (PMID 25122007, 2014). "In addition, LAG-3-deficient B6.SJL mice not only had increased susceptibility to Hg-induced autoimmunity but were also unresponsive to tolerance induction." (PMID 25122007, 2014). "In addition, our results indicate that LAG-3 expression on CD4+ T cells is critical for its regulatory role in Hg-induced autoimmunity since transfer of normal CD4+ T cells to LAG-3-deficient mice partially corrects their phenotype." (PMID 25122007, 2014). "We therefore hypothesized that transfer of wild-type CD4+ T cells might correct the increased susceptibility to autoimmunity in Lag-3−/− mice." (PMID 25122007, 2014). "That the increase of LAG3 levels by IFN-β may serve to attenuate cell activation in both B and T cells is in line with the modulatory role attributed to IFN-β in MS, the augmentation of autoimmunity by LAG3 deficiency, and the increased activation of B cells occurring in MS." (PMID 25025430, 2014). "Preclinical evidence showed that mice deficient in both LAG-3 and PD-1 developed severe myocarditis, suggesting that LAG-3 acts synergistically with PD-1 to prevent autoimmunity." (PMID 39225869, 2025). "Coinhibitory molecule LAG3 is best studied in regulating effector and regulatory T cell functions in autoimmunity, infection, and cancer." (PMID 40359031, 2025). "LAG-3 is a checkpoint molecule that regulates T-cell activity and contributes to the balance between immune activation and tolerance in cancer, autoimmunity, and other diseases." (PMID 41383640, 2025). "In this review, we provide an overview of the research conducted in recent years on LAG-3, covering its fundamental aspects, clinical applications, and its role in both autoimmunity and antitumor immunity." (PMID 39331884, 2024). "Red clusters further investigate the functions of LAG-3 in autoimmunity, tumor immunity, and targeted immunity, with most articles published from 2005 to 2015." (PMID 38390331, 2024). "Although the precise mechanism remains elusive, LAG3 is suggested to be pivotal in negatively regulating T-cell function, thus protecting against tissue damage and autoimmunity." (PMID 38617537, 2024). "The proliferation, activation, and effector function of CD4+ and CD8+ T-cells were negatively modulated by LAG3 expression, which has also been reported to regulate autoimmunity." (PMID 39698464, 2024). "While the present emphasis is on generating LAG3 antagonists for cancer immunotherapy that decrease inhibitory signaling, there is growing interest in developing LAG3 agonists to treat autoimmunity by increasing inhibitory signaling." (PMID 38556085, 2024). "These evidences verify the function of FGL1 regulating autoimmunity and immune homeostasis via binding to lymphocyte-activation gene 3 (LAG-3) to inhibit T cell activation." (PMID 37153794, 2023). "Lymphocyte-activation gene 3 (LAG-3) is an essential ICP that has been implicated in cancer, infectious disease, and autoimmunity." (PMID 37946301, 2023).
Autoimmunity (continued). "Although the phenotype of LAG-3−/− mice has been underwhelming, non-obese diabetic (NOD)-LAG-3−/− mice develop T-cell-driven autoimmune diabetes very rapidly, and LAG-3−/− mice are more prone to mercury-induced autoimmunity." (PMID 35265944, 2022). "LAG3 (Lymphocyte Activating 3) is a key immune checkpoint molecule negatively controlling immune response in cancer, infectious diseases and autoimmunity." (PMID 36224560, 2022). "Accumulating evidence indicates that LAG-3 is an inhibitory coreceptor that plays pivotal roles in autoimmunity, tumor immunity, and anti-infection immunity." (PMID 35300340, 2022). "Current data suggests that modulating LAG-3 can impact autoimmunity, cancer and chronic viral infection." (PMID 33995362, 2021). "The phenotypes of Tim-3−/− and Lag-3−/− mice are exceptionally mild, and either autoimmunity needs to be induced in the mice, or genetically permissible background is necessary, respectively, in order for the phenotype to be manifested." (PMID 33800368, 2021). "In contrast, mice with the double knockouts of LAG-3 and PD-1 have lethal autoimmune disorders, including myocarditis and pancreatitis." (PMID 33968036, 2021). "Second, mutations in other immune checkpoint molecules (e.g., PD1/PD-L1 or LAG3) will probably give rise to as-yet-undiscovered autoimmunity disorders, unless they impair other, even more vital (immune regulatory) mechanisms such as materno-fetal tolerance." (PMID 33996698, 2021). "Lymphocyte activation gene-3 (LAG3) is another immunotherapy target in the clinic, whose up-regulation is required to prevent the onset of autoimmunity." (PMID 32859214, 2020). "LAG3 is an important immune checkpoint with relevance in cancer, infectious disease and autoimmunity." (PMID 33488626, 2020). "Another study using antibiotic-treated mice, demonstrated that the gut microbiota promotes intraepithelial lymphocytes which plays a critical role in suppressing autoimmunity in the central nervous system via a LAG-3-dependent mechanism." (PMID 32802959, 2020). "As an immune regulator, LAG3 have a high affinity with MHC-II molecules to play a role in multiple autoimmune disorders." (PMID 31847878, 2019). "Despite LAG3’s importance in cancer, allergy, autoimmunity, and infectious disease, much about its function is undefined." (PMID 30653605, 2019). "The membrane protein LAG3 negatively regulates T cell function involving in suppressing central nervous system autoimmunity." (PMID 31847878, 2019). "This phenotype let us discover synergistic cooperation of LAG-3 and PD-1 in preventing overt autoimmunity and keeping immune homeostasis." (PMID 30603054, 2018). "LAG3 showcases the interest in the field of autoimmunity as several studies show that LAG3-targeting antibodies can also be used for the treatment of autoimmune diseases." (PMID 28934318, 2017). "Forced expression of EGR2 in naïve T cells converts them into LAG3 expressing and IL-10 secreting regulatory cells while EGR2 deficiency results in lupus-like autoimmunity, as well as increased STAT3 phosphorylation and IL-17 secretion." (PMID 25880134, 2015). "LAG3 was shown to reduce antigen-induced T cell expansion, to limit memory T cell pools, and to prevent various types of autoimmunity in mice." (PMID 25880134, 2015). "Our study adds autoimmunity to the list of pathological situations such as infections, cancer, and transplantation where LAG-3 can inhibit immune responses." (PMID 25122007, 2014). "Hg elicits higher cytokine production in LAG-3-deficient animals and adoptive transfer of wild-type CD4+ T cells can partially rescue LAG-3-deficient B6.SJL mice from Hg-induced autoimmunity." (PMID 25122007, 2014). "To understand the impact of homeostatic balance on environmentally-induced autoimmunity, we sought to investigate the role of LAG-3 in mercury-induced autoimmunity." (PMID 25122007, 2014).